MAPT (microtubule associated protein tau)
Diseases named in the same sentence as MAPT in open-access papers (continued):
Sharing a sentence is not in itself a finding about the gene and the disease.
breast carcinoma (continued). "A thorough analysis of the cancer genome atlas (TCGA) cohorts in tumors with high or low TAU expression, demonstrates a positive correlation between MAPT transcription and overall survival of patients with breast cancer." (PMID 33207722, 2020). "High rates of MAPT positivity have been reported from several other important cancer types including 43–52% in breast cancer, 63–74% in ovarian cancer, and 55–70% in gastric cancer." (PMID 30823906, 2019). "The over-expression of ANLN and KIF2C, and the under-expression of MAPT consistently showed a strong correlation with poor survival in the breast cancer patients from both validation datasets." (PMID 21679412, 2011). "Specifically, over-expression of ANLN and KIF2C, and under-expression of MAPT strongly correlated with poor outcomes in breast cancer patients." (PMID 21679412, 2011). "MAPT isoform expression in breast cancer tissues must be examined in detail to determine the exact correlation between MAPT expression and response to taxanes." (PMID 20579400, 2010). "Fulvestrant assists taxane function by downregulating the ER and ER-regulated factors associated with taxane resistance, and the combination of fulvestrant with taxanes increases the sensitivity of MAPT- and ER-positive breast cancer cells to taxanes." (PMID 20579400, 2010). "The second finding in the study involved clarification of the effect of the ER on the MAPT protein level in breast cancer cells." (PMID 20579400, 2010). "Expression of MAPT protein isoforms of less than 70 kDa is correlated with a low sensitivity to taxanes in breast cancer cells." (PMID 20579400, 2010). "The correlation between MAPT expression and sensitivity to taxanes was investigated in 12 human breast cancer cell lines." (PMID 20579400, 2010). "MAPT mRNA expression was assessed using quantitative real-time PCR and MAPT protein expression was assessed using Western blot analysis in 12 human breast cancer cell lines." (PMID 20579400, 2010). "In our study in ER-positive and MAPT-positive breast cancer cell lines, expression of MAPT protein isoforms of less than 70 kDa, which have a large impact on sensitivity to taxanes, was affected by ER signaling." (PMID 20579400, 2010). "In this study, we examined the correlation of MAPT expression with the sensitivity of human breast cancer cells to taxanes, and the relationship between ER and MAPT." (PMID 20579400, 2010). "Five ARLs (MAPT.IT1, AL133467.1, AC004585.1, AC055854.1, and LINC02613) were identified as protective factors, whereas two (LINC01614 and C6orf99) were identified as risk factors for breast cancer." (PMID 38189818, 2024). "MAPT is a microtubule-related protein tau, which can inhibit the function of taxanes, and its high expression reduces the sensitivity to taxanes, which is of great significance in breast cancer research." (PMID 37316840, 2023). "The data of these independent experiments therefore verified the hypotheses generated using bioinformatics analysis, indicating that GRSF1 and MAPT might play a vital role in tamoxifen resistance in breast cancer." (PMID 34406386, 2021). "Estrogen receptor signaling has also been shown to influence the expression of microtubule-associated protein tau (MAPT) such that the ER inhibitor fulvestrant can promote MAPT downregulation and thereby increase breast cancer cell sensitivity to taxane-based chemotherapy." (PMID 34661511, 2021). "Other genes, such as ESR1 (logFC 6.02); GATA3 (logFC 3.88); ERBB4 (logFC 3.0); AR (logFC 2.94); CCDC170 (logFC 2.79); MAPT (logFC 2.45); PGR (logFC 2.91); PIP (logFC 5.42) in immunoglobulin G-binding protein from this cluster were closely associated with breast cancer progression." (PMID 32182819, 2020). "MAPT has been proposed as a predictive marker of taxane responsiveness in breast cancer." (PMID 21209903, 2010).
breast carcinoma (continued). "In this study, we examined the relationship between the MAPT expression and the sensitivity to taxanes, the effect of ER expression or modulation on MAPT expression, and the combined impact of hormones and taxanes on anti-cancer activity and taxane resistance in breast cancer cell lines." (PMID 20579400, 2010). "The relationship between estrogen receptor (ER) and MAPT in breast cancer is unclear." (PMID 20579400, 2010). "The ER plays a key role in the development and progression of breast cancer, but it is unknown if ER stimulation induces MAPT expression in breast cancer cells." (PMID 20579400, 2010). "In addition to the correlation between MAPT and β-tubulin III levels and paclitaxel resistance in gastric cancer, downregulation of MAPT was also shown to improve taxane response in breast cancer cell lines and in ovarian cancer three-dimensional collagen I matrix culture." (PMID 27184254, 2016). "We also found that the expression of KDM7A was upregulated in chemoresistant cells (MCF-7/Adr and MCF-7/Tax), while MAPT and PP14571 were downregulated compared with the chemosensitive breast cancer control cell group (MCF-7/Con)." (PMID 34661511, 2021). "Using breast cancer cell lines and tissue samples, we confirmed that GRSF1 was significantly up-regulated and MAPT was down-regulated in the tamoxifen-resistant group compared with the tamoxifen-sensitive group." (PMID 34406386, 2021). "MAPT expression was highly variable, with brain glioblastoma multiforme (GBM), lower grade glioma (LGG), and neuroendocrine (pheochromocytoma and paraganglioma, PCPG) tumors showing the highest expression followed by breast cancer (BRCA)." (PMID 37730697, 2023). "The negative correlation between CDA and MAPT transcript levels was significant in cancers of several tissues, including breast cancer, papillary, and clear cell kidney carcinomas, prostate adenocarcinoma, and pheochromocytoma and paraganglioma." (PMID 28947735, 2017). "In support to the present findings, however, ER positive breast cancer cell lines were ixabepilone sensitive, while MAPT mRNA expression was not included in gene expression sets predictive of ixabepilone response in a very recent study." (PMID 23935969, 2013). "Low mRNA and protein expression of MAPT was correlated with high expression of TUBB3, which showed prognostic significance with disease-free survival and overall survival in patients with early breast cancer." (PMID 24369726, 2013). "Previous research has suggested that the absence of MAPT expression may serve as a criterion for identifying gastric and breast cancer patients likely to respond positively to paclitaxel therapy." (PMID 40296916, 2025). "We examined this issue by reducing the prevalence of breast cancer samples (i.e., we only used a half number of breast cancer patients, including 606/1212 randomly selected patients), and we identified a new signature including 7 genes CDK1, AP1S1, CASP3, MAP1LC3A, SNCA, MAPT, and GSK3B." (PMID 38642129, 2024). "The gene MAPT in this region, tagged by SNPs of the PD‐PRS, was already known as a potential predictive marker in epithelial ovarian cancer patients treated with paclitaxel/platinum first‐line chemotherapy and as a marker of paclitaxel sensitivity in breast cancer." (PMID 36788297, 2023).
amyotrophic lateral sclerosis (25 papers, 2013 to 2025). Amyotrophic lateral sclerosis (ALS) is a neurodegenerative disease characterized by progressive muscular paralysis reflecting degeneration of motor neurons in the primary motor cortex, corticospinal tracts, brainstem and spinal cord. "Mutations in the MAPT gene are associated with amyotrophic lateral sclerosis, while skeletal muscle autophagy can be regulated through MAPT." (PMID 32349667, 2020). "Familial forms of FTLD-tau are associated with mutations in the MAPT gene that encodes the tau protein, whilst mutations in Granulin (GRN), Valosin Containing Protein (VCP), or C9ORF72 genes can cause FTLD-TDP or amyotrophic lateral sclerosis." (PMID 23666556, 2013). "AEP has previously been reported to cleave aggregate-forming proteins, such as amyloid precursor protein (APP), microtubule associated protein tau (MAPT) and TAR-DNA binding protein 43 (TDP43) and is also implicated in an FTLD-related disorder, amyotrophic lateral sclerosis (ALS)." (PMID 34344440, 2021). "Compared to MAPT, GRN mutations are characterized by higher phenotypic variability, including FTD, amyotrophic lateral sclerosis (ALS), typical Parkinson’s disease (PD), and dementia with Lewy bodies (DLB)." (PMID 40722695, 2025). "Furthermore, ASOs have shown promising efficacy in targeting Huntington's gene (HTT) for Huntington's disease (HD), targeting SOD1 and C9ORF72 for amyotrophic lateral sclerosis (ALS), and targeting MAPT (TAU) for AD." (PMID 39226164, 2024).
Atrophy (25 papers, 2010 to 2026). Any weakening or degeneration, especially through lack of use. "Volume loss occurs around 15 years before expected onset in MAPT mutation carriers, with a faster annual rate of atrophy compared with other genetic forms of FTD." (PMID 34458729, 2021). "The neuroimaging data that were available for seven MAPT mutation carriers showed bilateral frontal and/or parietal atrophy with only mild asymmetry in four patients." (PMID 33467748, 2021). "The strongest association between MAPT expression and the atrophy pattern in symptomatic MAPT mutation carriers was measured with microarray probe A_24_P224488, which showed a non-significant positive association z = 0.867 (PFDR=0.15)." (PMID 33210084, 2020). "Uncorrected findings of atrophy were observed in MAPT mutation carriers in the anteromedial temporal and orbitofrontal lobes, and in striatum, frontal, temporal, and parietal areas of GRN carriers." (PMID 29172163, 2018). "The GRN mutation group showed asymmetrical atrophy whereas the MAPT group showed symmetrical atrophy." (PMID 20045477, 2010). "Some atrophic patterns may suggest FTD associated with genetic mutations: pronounced bitemporal atrophy occurs in patients with a MAPT mutation; markedly asymmetric frontotemporal atrophy is common in patients with a progranulin (GRN) mutation." (PMID 36533158, 2022). "We used visual rating scales to investigate whether identifying atrophy in these areas may be helpful in distinguishing symptomatic patients carrying different causal mutations in the microtubule-associated protein tau (MAPT), progranulin (GRN) and chromosome 9 open reading frame (C9ORF72) genes." (PMID 29793546, 2018). "However, in identifying parallel changes in FDG-PET and volumetric data in the anterior cingulate, it is difficult to be clear from this cross-sectional study alone whether hypometabolic change appeared before or concurrently with regional atrophy in P301L MAPT mutation carriers." (PMID 33568215, 2021). "Across different subtypes of MAPT mutations (IVS10+16, IVS10+3, N279K, S305N, P301L, and V337M), similar patterns of atrophy were reported in the later symptomatic phase." (PMID 32184751, 2020). "Even in regions where the rate of volume loss increased between the mild and symptomatic stages in C9orf72+ carriers, the magnitude of acceleration of atrophy between these 2 stages was much higher in MAPT+ and GRN+ carriers." (PMID 33112398, 2020). "C9orf72 repeat expansion carriers had a greater degree of atrophy, as compared to GRN mutation carriers and MAPT mutation carriers, with the latter being the smallest group in our sample." (PMID 28460069, 2017). "Using an average of the best performing direct measure, the current study reports a similar pattern of results, with annual atrophy rates of 1.8 (0.9)% in MAPT, 1.6 (1.1)% for C9orf72 and 3.1 (2.0)% for GRN patients, who conclusively exhibit the highest rate of change across subgroups." (PMID 34626889, 2021). "In GRN- and MAPT-associated FTD, striatal atrophy is related to impaired social cognition." (PMID 34458729, 2021). "Compared with the other genetic groups, MAPT+ tends to exhibit atrophy more focally and symmetrically, which could improve the power to detect atrophy at the group level." (PMID 33112398, 2020). "It is unclear why fewer are seen in these two groups although this may be related to underlying atrophy of the basal ganglia which tends to be seen in the GRN and MAPT groups to a greater extent than in the C9orf72 group." (PMID 28529873, 2017). "Even genetic variants implicated in FTD show a similar pattern, where patients with MAPT mutations have greater left‐sided frontal atrophy, while those with the GRN mutation had greater right‐sided atrophy, and C9ORF72 carriers tended to show a symmetric pattern of atrophy." (PMID 28031997, 2016).
Atrophy (continued). "The change of functional connectivity was observed early in the disease course even without gray matter loss in asymptomatic MAPT mutation carriers, suggesting that functional abnormalities may precede the occurrence of atrophy in these regions." (PMID 32184751, 2020). "Structural neuroimaging in patients with C9orf72 expansions does not reveal a characteristic pattern of atrophy, unlike GRN or MAPT mutations." (PMID 26388768, 2015). "These maps and plots revealed that variability was highest in MAPT+ and lowest in C9orf72+ carriers, suggesting that excessive variability across C9orf72+ carriers, either in the spatial location of atrophy or the rate of atrophy, does not account for the group-level findings." (PMID 33112398, 2020). "In the full cohort, normative expression of MAPT, PINK1, and PSEN2 predicted regional atrophy after correction for spatial autocorrelation, although none survived multiple-testing correction." (PMID 41991538, 2026).
Brain atrophy (24 papers, 2013 to 2025). Partial or complete wasting (loss) of brain tissue that was once present. "First, it is noteworthy that the temporal dominant patterns of brain atrophy have been associated with mutation in the MAPT gene." (PMID 37762113, 2023). "This is supported by the finding that pre-symptomatic FTD causing mutant MAPT carriers had intermediate levels of brain atrophy compared to symptomatic carriers but comparable glucose hypometabolism." (PMID 35281504, 2022). "Hypometabolism in the temporal lobe and anterior cingulate cortex was reported in asymptomatic MAPT mutation carriers, while temporal lobe hypometabolism even preceded the brain atrophy on MRI in the asymptomatic stage." (PMID 36051222, 2022). "Imaging study results showed asymmetric atrophy in the inferior frontal, temporal, and inferior parietal lobes, whereas C9orf72 or MAPT mutations are associated with symmetrical brain atrophy." (PMID 30846947, 2019). "Brain atrophy visualized on structural MRI and pathological cerebrospinal fluid (CSF) concentrations of microtubule-associated protein tau (T-tau) and phosphorylated microtubule-associated protein tau indicate neurofibrillary degeneration." (PMID 28583116, 2017). "Longitudinal MRI studies of brain atrophy suggest that MAPT mutations are associated with an atrophy rate intermediate between those of GRN and C9ORF72." (PMID 25556536, 2015). "Initially, in relation to GRN genetic mutation, it appears that individuals with bvFTD carrying GRN mutations demonstrate a faster rate of whole brain atrophy, suggesting a more rapid disease progression, compared to patients carrying other genetic variations, such as MAPT." (PMID 37762113, 2023). "Comprehensive neuropsychological assessments, FDG and tau PET scans, and plasma NfL and GFAP levels are useful and more sensitive than evaluating symptoms and visual reading of brain atrophy on MRI in the early identification of genetic svPPA patients with the MAPT mutation." (PMID 36707904, 2023). "Neuroimaging studies revealed brain atrophy in the anterior temporal, orbitofrontal, caudate, insula, and anterior cingulate cortices, and different MAPT mutations may target different brain areas." (PMID 30846947, 2019). "There is initial evidence that neuroinflammation may precede abnormal protein aggregation and brain atrophy in pre-symptomatic carriers of MAPT mutations, although further studies are needed to confirm these preliminary findings in AD or other neurodegenerative diseases." (PMID 31320450, 2019). "These shared genes that are commonly expressed in regions more spared by cortical atrophy in C9orf72-bvFTD and GRN-bvFTD, and conversely, these genes are commonly expressed in regions more vulnerable to brain atrophy in MAPT-bvFTD." (PMID 39920674, 2025). "A recent study explored co-expression patterns associated with brain atrophy patterns in symptomatic FTD mutation carriers in C9orf72, GRN, and MAPT and report top 20 genes and relevant biological pathways." (PMID 38469573, 2024). "Brain atrophy was extensive in fronto-insulo-parietal regions classically affected in FTD and in MAPT mutations." (PMID 36474176, 2022). "In symptomatic MAPT V337M mutation carriers, the tau accumulation assessed by [18F] AV1451 tracer was also associated with regional brain atrophy by structural MRI." (PMID 32184751, 2020). "A longitudinal study with pre-symptomatic PGRN and MAPT mutation carriers identified hypoperfusion independent of brain atrophy before symptomatic disease." (PMID 35281504, 2022). "MAPT KI mouse did not display acceralated neuroinflammation, neuronal cell death and brain atrophy." (PMID 31160584, 2019).
Huntington disease (19 papers, 2013 to 2026). Huntington disease (HD) is a rare neurodegenerative disorder of the central nervous system characterized by unwanted choreatic movements, behavioral and psychiatric disturbances and dementia. "Interestingly, in EE conditions, the microtubule-associated protein tau was found less phosphorylated at the 705 serine residue in Huntington’s disease compared with WT mice." (PMID 36523271, 2022). "We next examined the relationship between cognitive function and five genetic polymorphisms linked to genes known to affect cognitive function in Huntington’s disease: MSH3, FAN1, MAPT, BDNF and COMT." (PMID 36519153, 2022). "In terms of genetic polymorphisms, we selected common polymorphisms that have been previously associated with cognitive function in Huntington’s disease [COMT, brain-derived neurotrophic factor (BDNF), FAN1, MSH3 and MAPT]." (PMID 36519153, 2022). "Recently the microtubule associated protein tau, MAPT, which is associated with several neurodegenerative disorders, has been implicated in Huntington’s disease." (PMID 25953777, 2015). "In Huntington’s disease (HD), alternative splicing alteration emerged as a molecular mechanism in view of individually reported mis-splicing events in neurodegeneration-linked genes such as HTT itself, MAPT and TAF1." (PMID 41928095, 2026).
amyloid (18 papers, 2014 to 2025). "According to current evidence as follows, Aβ, microtubule-associated protein tau and transthyretin amyloidosis (ATTR) may be the key proteins in bridging CAA and CA." (PMID 36910141, 2023). "The expression ratio between 4 and 3R tau was similar between dKI and MAPT KI mice, even when the mice aged, suggesting that amyloidosis didn’t affect the alternative splicing of MAPT gene." (PMID 38462606, 2024). "In contrast, exonic and intronic mutations in MAPT, the gene encoding Tau, are associated with neurodegenerative diseases, but not with AD, and hence do not result in amyloid pathology." (PMID 25407337, 2014). "MAPT, APP, PSEN1, and BACE1 are key proteins involved in the pathological hallmarks of AD, namely neurofibrillary tangles and amyloid plaques." (PMID 41195325, 2025). "3xTG mice express three transgenes (APP Swedish, MAPT P301L, and PS1 M146V) and develop amyloid plaque pathology starting around 4 months, with aggregated tau pathology beginning around 12 months." (PMID 32733196, 2020).